TSPO (translocator protein)
Diseases named in the same sentence as TSPO in open-access papers (continued):
Sharing a sentence is not in itself a finding about the gene and the disease.
heart failure (9 papers, 2016 to 2022). Inability of the heart to pump blood at an adequate rate to meet tissue metabolic requirements. "Interestingly, heart failure is associated with increased TSPO expression and cardiac-specific TSPO KO mice are protected from pressure-overload-induced cardiac remodeling and dysfunction." (PMID 32528313, 2020). "Likewise, the early brain TSPO signal at 3 days post-MI was proportional to the chronic brain TSPO signal at 8 weeks (r = 0.466, p = 0.005), suggesting that early microglial activation may predispose the brain to later dysfunction during heart failure." (PMID 32125488, 2020). "Immunostaining of heart failure remote myocardium also suggests localization to mitochondria in cardiomyocytes, which aligns with the regulation of TSPO in heart failure." (PMID 32125488, 2020). "Our results yield several key findings with respect TSPO function in pressure-overload induced heart failure (TAC)." (PMID 30385779, 2018). "Further studies using a murine model of infarcted heart or clinical heart failure controls would be needed to optimize the TSPO-targeting PET imaging for allogeneic iPS cell therapy for the heart." (PMID 27930666, 2016). "The increase in cardiac TSPO signal after cerebral stroke may be indicative of mitochondrial dysfunction and increased exome cycling, as described recently in mouse models of heart failure." (PMID 36279013, 2022). "Therefore, TSPO is likely to be a valuable target to investigate in the setting of myocardial inflammation in heart failure." (PMID 34485416, 2021). "Together, these data confirm the adverse effect of TAC-induced heart failure on ATP production and suggest that the effects of the TSPO-KO cardioprotection after TAC may be mediated by enhancement of energy production via complex I." (PMID 30385779, 2018). "However, in noninfarcted myocardium in other MI or cardiomyopathy models of heart failure, there is significant TSPO expression, indicating that TSPO may have a wider role in the failing heart." (PMID 32859708, 2021). "As such, TSPO PET imaging in chronic heart failure appears to provide a surrogate measurement of mitochondrial density which may be helpful for assessing ventricular remodeling and response to heart failure therapies." (PMID 32125488, 2020).
lung carcinoma (9 papers, 2016 to 2025). "Therefore, treatment with MGV-1 and 2-Cl-MGV-1 was helpful in preventing TSPO-associated lung cancer." (PMID 38585455, 2024). "In the current study, we aim to examine the protective capacity of our TSPO ligands exhibiting low affinity, MGV-1 and 2-Cl-MGV-1, against the TSPO-related mitochondrial damages caused by CS exposure, which lead to cell death, mainly apoptotic cell death in H1299 lung cancer cells." (PMID 34063262, 2021). "At the same time, there is evidence indicating the direct involvement of the TSPO in the regulation of the mPTP in various pathologies, in particular, ischemia/reperfusion in cardiomyocytes, as well as in the lung cancer cells in cases of damage caused by cigarette smoke." (PMID 32722345, 2020). "TSPO has also been implicated in lung cancer development, as cigarette smoke exposure was found to alter TSPO protein, leading the way for the initiation and progression of lung cancer." (PMID 27608010, 2016). "Their study indicated that while TSPO mRNA expression is elevated in liver, prostate, kidney, and brain cancers, it is lower in colon and lung cancers, suggesting tissue‐specific expression patterns and roles." (PMID 40550494, 2025). "In the current study, H1299 lung cancer cell line exposed to CS for various time periods (30 mins, 60 mins and 120 mins) and TSPO expression and cell death processes were studied." (PMID 31295884, 2019). "TSPO is upregulated in liver, breast, and pancreatic cancers, while significantly downregulated in colon and lung cancers, resulting in differential effects on the biological phenotype of tumor cells." (PMID 40842566, 2025). "Furthermore, the density of TSPO is between 3000–4000 fmol/mg protein in both H1299 lung cancer cells and BV-2 microglial cells." (PMID 36291606, 2022). "TSPO is involved in cigarette smoke (CS)-induced cellular toxicity, which may result in oral and pulmonary diseases and lung cancer." (PMID 34063262, 2021). "Since TSPO is involved in metabolic pathways relevant to cell death, inflammation and mitochondrial activities, we hypothesized that the toxic effects of CS on human lung cancer cell line are dependent on alterations in the TSPO expression." (PMID 31295884, 2019). "Moreover, the relationship between upregulation of TSPO and lung cancer is unclear." (PMID 34063262, 2021). "To explore TSPO expression in tumors, we analyzed data from the TIMER database and found that TSPO mRNA expression varied depending on tumor type, with notably high expression in liver cancer and comparatively low expression in lung cancer." (PMID 40842566, 2025).
prostate carcinoma (9 papers, 2016 to 2025). A carcinoma that arises from epithelial cells of the prostate gland. "The 18-kDa translocator protein (TSPO) levels are associated with brain, breast, and prostate cancer progression and have emerged as viable targets for cancer therapy and imaging." (PMID 27399688, 2016). "Genes involved in steroid synthesis included CYP21A2, HSD17B2, ITGA6, IDI2, MAP2K1, PMVK, TSPO, and may correspond to androgen dependent growth of prostate cancer." (PMID 32226005, 2020). "Moreover, studies have shown that that TSPO expression correlates positively with the invasiveness and/or malignancy of breast, colorectal and prostate cancers." (PMID 27608010, 2016). "Moreover, elevated TSPO levels are well documented in oncology and have been correlated with tumor proliferation, invasion, and metastasis including brain, colorectal, liver, breast, oral cavity, and prostate carcinomas." (PMID 27399688, 2016). "However, there are no data currently available that provide information on the expression of TSPO in the brain of patients of prostate cancer with and without ADT." (PMID 37885823, 2023). "As all subjects in our study were patients with prostate cancer on ADT, it was not possible to distinguish whether this correlation between CRT activation and TSPO uptake is a feature specific to ADT treatment or to prostate cancer." (PMID 37885823, 2023).
brain cancer (8 papers, 2015 to 2025). A primary or metastatic malignant neoplasm affecting the brain. "The 18-kDa translocator protein (TSPO) is a potential mitochondrial target for drug delivery to tumors overexpressing TSPO, including brain cancers, and selective TSPO ligands have been successfully used to selectively deliver drugs into the target." (PMID 27322261, 2016). "Another interesting target identified was the TSPO -(Translocator protein) that is known to be expressed exclusively in brain cancers, including GBM, and can be used for delivering drugs across the blood brain barrier along with DNA topoisomerase I (TOP1), Lipoprotein Lipase (LPL), and DNMT1." (PMID 37637064, 2023). "However, radiolabelled TSPO ligands have shown high sensitivity for detecting the levels of TSPO protein in prostate and brain cancer." (PMID 30044440, 2018). "All these findings together suggest that TSPO may serve as a biomarker for brain cancer." (PMID 31661894, 2019). "This system is highly effective for treating tumors that overexpress mitochondrial TSPO, such as some types of breast, colorectal, prostate, and brain cancers, while it is ineffective in TSPO-negative cancer cells." (PMID 31948035, 2020).
colon carcinoma (8 papers, 2015 to 2025). "The HT-29 human colon carcinoma cell line has been described as a model of intestinal epithelial cells expressing TSPO." (PMID 27054921, 2016). "We used HT-29 human colon carcinoma cells to evaluate the role of TSPO and its drug ligands in tumor necrosis factor (TNF)-induced inflammation." (PMID 27054921, 2016).
COVID-19 (8 papers, 2021 to 2026). A disease caused by infection with severe acute respiratory syndrome coronavirus 2. "However, lower WM TSPO availability in individuals with longer LC duration suggests COVID-19-associated neuroinflammation may subside with time, while the association between limbic TSPO availability and LC severity may imply a role for limbic activity in LC symptomology." (PMID 42059960, 2026). "The TSPO VT in the dorsal putamen of COVID-19 cases negatively correlated with motor speed." (PMID 37256580, 2023). "TSPO and MRC1 were highly expressed in macrophage clusters enriched in healthy controls and moderate COVID-19 patients." (PMID 34239034, 2021). "We investigate whether the translocator protein standardized uptake value ratio (TSPO SUVr), a quantifiable marker of neuroinflammation using positron emission tomography (PET), is elevated in the brains of patients with post-COVID-19 active TLE." (PMID 41616056, 2026). "Both the increase of TSPO in blood vessels and perivascular GFAP could point to disruption of the BBB following SARS-CoV-2 infection, also witnessed in COVID-19 patients." (PMID 37516868, 2023).
diabetes (8 papers, 2018 to 2025). "Among the four genes (PHIP, TRPM3, SPTY2D1 and TSPO) associated with fasting insulin and combined into a genetic risk score, we showed that carriers of insulin increasing risk alleles had higher odds of developing diabetes and impaired fasting glucose at follow-up." (PMID 35665752, 2022). "Our understanding of the role of TSPO in diabetes will expand by combining insights gained from pharmacological and genetic studies targeting this critical outer mitochondrial membrane protein in the diabetic heart." (PMID 30416455, 2018). "Diabetes significantly increased by 3.4-fold the protein levels of TSPO in the retina of diabetic animals (p < 0.01) when compared with the control condition (saline-injected retinas from non-diabetic animals), and this effect was abolished by the A2AR antagonist." (PMID 31748653, 2019). "The Papadopoulos laboratory postulated that TSPO in adipose tissues could serve as a pharmacological target in the treatment of type-2 diabetes mellitus." (PMID 30416455, 2018). "Finally, we provide our perspective on the role of TSPO in the pathophysiology of diabetes, in general and diabetes-related arrhythmias, in particular." (PMID 30416455, 2018). "In a rat model of obesity and type-2 diabetes mellitus, in which we and others found that classically cardioprotective pathways targeting mitochondria are generally impaired, we verified the effectiveness of TSPO inhibition by 4′-chlorodiazepam in protection against these arrhythmias." (PMID 30416455, 2018). "This provides a plausible link between non-myocyte TSPO activity and arrhythmogenesis, especially in the setting of diabetes mellitus." (PMID 30416455, 2018).
Arthritis (7 papers, 2013 to 2022). Inflammation of a joint. "Imaging characteristics of arthritis can be further improved by usingthe second generation TSPO tracer [11C]DPA-713." (PMID 31553762, 2019). "In the arthritis rat model, immunohistochemistry confirmed the presence of TSPO-positive inflammatory cells in the arthritic knee." (PMID 24625077, 2014). "Intra-articular injection of mBSA in the right knees of immunized rats provoked development of arthritis which was characterized by an influx of TSPO-positive cells in the synovium as shown by immunohistochemical staining." (PMID 24625077, 2014). "Previously, the potential of imaging (sub)clinical arthritis was demonstrated by targeting the translocator protein in activated macrophages using (R)-[11C]PK11195 and positron emission tomography (PET)." (PMID 23452511, 2013). "Non-invasive identification of arthritis activity by TSPO PET may have value for clinical applications of early diagnosis and therapy monitoring of RA, which should be further investigated in future studies." (PMID 31553762, 2019). "In the present study, both DPA tracers visualized arthritic joints independent of polymorphism status, suggesting a lack of effect of TSPO polymorphism status on arthritis targeting which would be an advantage for clinical implementation." (PMID 31553762, 2019). "In this study, the TSPO polymorphism status did not affect the comparisons between the TSPO tracers for arthritis imaging." (PMID 31553762, 2019). "The high expression of TSPO on macrophages has led to its use as a cellular target for the imaging of multiple inflammatory diseases; indeed, in the case of RA, TSPO-targeted imaging in vivo has been demonstrated to detect joint inflammation even before clinical signs of arthritis are apparent." (PMID 28968465, 2017). "Imaging of (sub)clinical arthritis by targeting the translocator protein (TSPO) on activated macrophages is feasible using (R)-[11C] PK11195-based positron emission tomography (PET), but clinical applications are limited by background uptake in peri-articular bone/bone marrow." (PMID 24625077, 2014). "Therefore, TSPO can also be used as an imaging marker for arthritis SMs." (PMID 35958604, 2022). "The purpose of the present study was to explore whether TSPO PET can be further optimized for arthritis imaging by investigation of the second generation TSPO PET tracers [18F]DPA-714 and [11C]DPA-713 for the first time in clinically active RA patients in a clinical proof of concept setting." (PMID 31553762, 2019). "Beyond the prototypical macrophage tracer [11C]-PK11195, targeting the translocator protein (TSPO) on activated macrophages, second-generation TSPO tracers showed improved properties over [11C]-PK11195 to visualize arthritis." (PMID 29681783, 2018). "In this study, the potential of the two high affinity TSPO PET tracers [11C]DPA-713 and [18F]DPA-714 for imaging activated macrophages in arthritis was evaluated using an mBSA-induced rat model of RA." (PMID 24625077, 2014). "This is in line with our previous findings, which showed that TSPO tracers including [11C]DPA-713 and [11C]PK11195 could possibly detect subclinical inflammation, which can precede development of clinical assessable arthritis later in time." (PMID 32365551, 2020). "Previously, feasibility of imaging (sub)clinical arthritis was demonstrated using the macrophage targeting PET tracer (R)-[11C]PK11195 (1-[2-chlorophenyl]-N-methyl-N-[1-methyl-propyl]-3-isoquinoline carboxamide), that binds to the translocator protein that is up-regulated in activated macrophages." (PMID 23452511, 2013).
liver fibrosis (7 papers, 2015 to 2024). "The translocator protein (TSPO), for instance, is a biomarker that can be targeted in molecular imaging for monitoring the progression of hepatic fibrosis to cirrhosis." (PMID 34298967, 2021). "Previous studies have suggested that radiotracers, such as [18F]FEDAC and [18F]PBR06, can monitor liver fibrosis by assessing the expression levels of TSPO." (PMID 34934405, 2021). "Additional studies using anti-TSPO antibody and anti-CD11b antibody for identifying Kupffer cells and macrophages in the liver are required to further reveal the pathology of liver fibrosis." (PMID 34934405, 2021). "TSPO has recently been considered as a useful biomarker of liver fibrosis, and the increased mRNA expression level of TSPO in rats with BDL was also confirmed in this study." (PMID 34934405, 2021). "They found that TSPO was expressed mainly in HSCs, the uptake of [18F]FEDAC in fibrotic livers was well correlated with TSPO expression, and TSPO mRNA levels increased with the level of liver fibrosis." (PMID 31341723, 2019). "In this study, we aimed to evaluate potential utility of TSPO as a molecular imaging biomarker for noninvasive monitoring of the progression of hepatic fibrosis to cirrhosis." (PMID 26612465, 2015). "Liver fibrosis developed progressively, and the numbers of TSPO-expressing HSCs and macrophages were increased progressively." (PMID 26612465, 2015). "In summary, we demonstrated that TSPO was a useful imaging biomarker for noninvasive monitoring of liver fibrosis." (PMID 26612465, 2015). "We then measured the uptake of [18F]FEDAC in livers using a PET scanner at various times after CCl4 treatment and evaluated the progression of hepatic fibrosis and the expression of TSPO by histological observation." (PMID 26612465, 2015). "In this study, we aimed to evaluate the utility of translocator protein (18 kDa) (TSPO) as a molecular imaging biomarker for monitoring the progression of hepatic fibrosis to cirrhosis." (PMID 26612465, 2015). "Our results demonstrated that PET imaging with the TSPO-specific radioprobe [18F]FEDAC permitted noninvasive visualisation of the progression from hepatic fibrosis to cirrhosis." (PMID 26612465, 2015). "To this end, in the present study, we aimed to examine whether TSPO could be used as a molecular imaging biomarker for the progression of hepatic fibrosis." (PMID 26612465, 2015). "TSPO-expressing macrophages and HSCs increased with the progression of liver fibrosis." (PMID 26612465, 2015). "TSPO was a useful molecular imaging biomarker and could be used to track the progression of hepatic fibrosis to cirrhosis with PET." (PMID 26612465, 2015). "Our data provide important insights regarding the utility of TSPO as a marker of hepatic fibrosis." (PMID 26612465, 2015). "Thus, PET imaging with the TSPO-specific radioprobe [18F]FEDAC may aid in the noninvasive visualization of liver fibrosis progression to cirrhosis in patients with chronic liver diseases." (PMID 38952717, 2024). "In the bile duct-ligated (BDL) rat model of liver fibrosis, the accumulation of [18F]FEPPA increases with the progression of liver injury and the expression levels of TSPO." (PMID 38952717, 2024). "Another TSPO radiotracer, 18F-FEDAC, has been used to monitor liver fibrosis in rats, as the signal correlated well with expression of TSPO in macrophages, which was increased with disease." (PMID 34485416, 2021). "[18F]FEPPA is another promising ligand for TSPO; however, the information obtained using [18F]FEPPA for evaluating liver fibrosis is missing." (PMID 34934405, 2021). "TSPO is expressed in HSCs, which are the major ECM-producing cells in liver fibrosis both in vitro and in vivo." (PMID 31341723, 2019). "Thus, TSPO may represent an effective biomarker for monitoring the progression of liver fibrosis." (PMID 26612465, 2015).
liver fibrosis (continued). "In this study, we found that the expression levels of hepatic TSPO, TGF-β1, PDGF-β, and TNF-α mRNAs were increased progressively by 6 weeks of CCl4 treatment, at which time liver fibrosis had almost developed into cirrhosis." (PMID 26612465, 2015). "Positively correlation between hepatic TSPO and (transforming growth factor) TGF-β1/(tumor necrosis factor) TNF-α mRNA expression suggests that macrophage M1 and M2 phenotypes intervene during liver fibrosis development." (PMID 29114179, 2017). "In this sense, surprising findings have been found in liver fibrosis where TSPO are not overexpressed in patients with hepatic encephalopathy." (PMID 29114179, 2017). "Thus, PET imaging studies with the TSPO-specific radioprobe [18F]FEDAC may be useful for noninvasive visualisation of the progression from hepatic fibrosis to cirrhosis in patients with chronic liver diseases." (PMID 26612465, 2015).